ACHE (acetylcholinesterase (Yt blood group))
Diseases named in the same sentence as ACHE in open-access papers (continued):
Sharing a sentence is not in itself a finding about the gene and the disease.
dementia (continued). "To elucidate the effect of two plant extracts (S. scardica and C. vulgare) and their combination on the acetylcholinergic neurotransmitter system in healthy rats and rats with experimental dementia, we assessed the changes in AChE activity in the cortex and hippocampus of the rodents." (PMID 38339117, 2024). "In rodent dementia models, unmitigated AChE release in the synaptic cleft exercabates oxido-inflammatory response and the aggregation of pathological proteins like Aβ peptides, while MAO-A and MAO-B polymorphisms have been linked with several neuropsychiatric diseases." (PMID 39210265, 2024). "Therefore, reversible inhibitors of AChE, such as galantamine, rivastigmine, and donepezil are often used in treatments of dementia." (PMID 38337955, 2024). "AChE, being the major enzyme degrading ACh, is crucial for proper cholinergic transmission and numerous studies have demonstrated that its inhibition improves memory and slows cognitive decline in patients with various types of dementia and in AD." (PMID 39683869, 2024). "Optically pure (−)-galanthamine, another traditional AChE inhibitor that has received clinical approval for the treatment of mild to moderate dementia in patients with AD, is also used in the development of potential radiopharmaceutical probes for imaging brain AChE." (PMID 37687094, 2023). "It was reported that the combination of an AChE inhibitor and an antioxidant can be a better therapeutic strategy and may prove to be promising in planning the ligands for treating the dementia." (PMID 37641690, 2023). "The cholinergic system is involved in the cognition process and its dysfunction due to the alteration of the activity of key enzymes such as acetylcholinesterase (AChE) and butyrilcholinesterase (BuChE), responsible for the onset of various dementias including AD." (PMID 37686262, 2023). "Eventually, increased levels of AChE in the blood have been considered a biomarker of dementia." (PMID 37509038, 2023). "Thus, an agent that inhibits both AChE and BuChE (a dual inhibitor), such as rivastigmine, provides greater benefits to patients with dementia by decreasing the compensatory effect of Ach hydrolysis by BuChE when AChE levels decrease." (PMID 36678592, 2023). "The synthesis of AChE inhibitors presents an efficient approach to diagnose the mental symptoms of AD (Alzheimer disorder) and other promising therapeutic applications in the management of ataxia, senile dementia, and Parkinson's disease." (PMID 35942378, 2022). "The biological activity of MACs in the Scop-induced model of dementia was conducted by behavioral observation and biochemically; the effects were compared with those of M. The molecular modeling predicted MACs’ affinity to bind to the active center of AChE." (PMID 36080227, 2022). "However, AChE overexpression is a reliable marker of aging, inflammatory states, and several diseases, such as hypertension, glaucoma, dementia, and anemia." (PMID 34682773, 2021). "Rivastigmine (RV), a phenyl carbamate ester, is a “pseudo-irreversible” dual inhibitor of acetylcholinesterase (AChE) and butyrylcholinesterase (BuChE) that is currently available as oral capsules for the treatment of mild to moderate dementia of the Alzheimer’s type." (PMID 33466880, 2021). "In addition, the effects of AChE inhibitors in elderly patients with dementia on symptoms of depression and anxiety have been studied." (PMID 34502198, 2021). "Furthermore, the inhibition rate for AChE enzymes known to degrade acetylcholine, a neurotransmitter, was measured to find out the anti-dementia effect." (PMID 34287737, 2021). "Higher impairment in AChE activity is observed in patients with dementia." (PMID 34502198, 2021). "Since HLJG0701-β exhibited AChE inhibitory effects, it may be able to enhance memory and prevent dementia, suggesting the possibility of its application as a therapeutic AChE inhibitor." (PMID 34070099, 2021).
dementia (continued). "The inhibition of AChE is one of the therapeutic strategies for dementia." (PMID 34204787, 2021). "Therefore, the inhibitors of acetylcholinesterase (AChE) are carefully studied, as they sustain the signal transmission between the neuronal synapses and limit the occurrence of etiological factors for dementia." (PMID 32260053, 2020). "However, a meta-analysis has shown a weight reduction among dementia patients treated with AChE inhibitors." (PMID 29929492, 2018). "Therefore, inhibition of AChE activity serves as a therapeutic target for the treatment of senile dementia, AD and Parkinson’s disease." (PMID 29740317, 2018). "Therefore, AChE inhibitors, ameliorating the hypofunction of the cholinergic system, have been focused on the therapeutic treatment of dementia, especially AD." (PMID 28272324, 2017). "Therefore, current therapeutic drugs that are based on the cholinergic system, such as AChE inhibitors (donepezil, galantamine), have been evaluated for treatment of AD and dementia." (PMID 26939918, 2016). "Our results are discussed in the context of AChE inhibitor therapy as used in dementia." (PMID 26506622, 2015). "AChEIs ameliorate dementia by inhibiting acetylcholinesterase (AChE) in the central nervous system." (PMID 23403922, 2013). "CSF AChE activity was lower in the other dementia group compared to all other study groups." (PMID 24312390, 2013). "In addition, CSF AChE activity was lower in patients with other dementias than that in patients with AD, SMCI or controls (P = 0.01, P = 0.01 and P = 0.002, respectively)." (PMID 24312390, 2013). "Consistent with previous studies in experimental dementia and scopolamine-induced mice, pioglitazone could inhibit AChE activity and restore ACh level in fructose-drinking insulin resistance rats." (PMID 23527159, 2013). "Also, acetylcholine esterase (AchE) is an enzyme which breaks down acetylcholine and is a well-known target and biomarker for memory dysfunction or dementia." (PMID 22675385, 2012). "Top proteins with high feature importance in the clinical impairment signature again highlighted ACHE and NPTXR as well as additional targets linked to neuroplasticity (EPHA4 and CNTFR) and immune activation (MSMP and KLK3), underscoring their potential for transdiagnostic dementia staging." (PMID 40665048, 2025). "The inhibition of AChE may also be a promising therapeutic approach for other forms of dementia." (PMID 39796512, 2024). "Therefore, the anti-dementia effect following ischemic stroke with metabolic syndrome of GCJ may involve the improvement of AChE, eNOS, BDNF, pERK/ERK, and neural plasticity." (PMID 37564141, 2023). "Nevertheless, it could be worthwhile to extend the findings of the present study to evaluation of potential sex differences or aging on sensitivity of NMJs to donepezil, or to other piperidine anti‐AChE compounds that may be prescribed for treatment of dementias." (PMID 36028305, 2022). "Reversible AChE inhibitors of various chemical structures have noteworthy pharmacological application in the treatment of neurological disorders such as myasthenia gravis, Lewy bodies and Parkinson’s disease dementia, and as well as prophylactics against nerve agent intoxication." (PMID 35455397, 2022). "It is known that they are not toxic, and the appropriate composition of the diet of people with AD and possible incorporation into the diet of functional products enriched with natural AChE inhibitors may be the beneficial strategy in the symptomatic therapy of dementia." (PMID 35745206, 2022). "Moreover, the inhibition of acetylcholinesterase (AChE) and butyrylcholinesterase (BChE), enzymes responsible for the hydrolysis of ACh following synaptic release, has thus been suggested as a promising strategy to avoid the progression of dementia." (PMID 36431805, 2022).
dementia (continued). "The activity of AChE in scopolamine-treated mice was the highest among all groups (p < 0.05), suggesting that a dysfunction of the cholinergic nervous system may facilitate the progression of dementia." (PMID 32679768, 2020). "Maybe AChE-Is can also influence this mechanism in dementia patients." (PMID 32024303, 2020). "The synthetic drugs currently used in AD have different limits and side effects, so the search for AChE inhibitors derived from plants has accelerated in recent years, and the benefits of these drugs are being studied not only for the treatment of AD, but also for other forms of dementia." (PMID 32155959, 2020). "Indeed, a study has shown that RBC AChE measurement might have the potential as a peripheral biomarker for diagnosis of familial Alzheimer’s and Parkinson’s disease dementia." (PMID 31680850, 2019). "Hence, AD and other form of dementia could be treated by the use of agents that restore the level of acetylcholine through the inhibition of both major form of cholinesterase enzymes AChE and BChE." (PMID 29169349, 2017). "Moreover acetylcholinesterase (AChE) inhibition may help in the treatment of Alzheimer’s disease (AD), as well as senile dementia, myasthenia gravis, Parkinson’s disease and ataxia, due to the associated cholinergic deficit." (PMID 26784465, 2013). "Here, exposure to silver and mercury salts elevated AChE and MAO levels in the neural tissues of cockroaches, reminiscent of increased hippocampal activity of AChE and MAO which potentiates Aβ peptide formation in dementia." (PMID 38970085, 2024). "The study carried out a calorimetric test (ITC) and docking simulation (DS) showing the activity of AChE inhibitors, which were 16 hydroxybenzoic acids, in order to select the most effective derivatives that could be safely used in the diet of people with dementia." (PMID 35745206, 2022). "In the present study, hydroxybenzoic acids were interacted with AChE by the ITC and DS methods, which allowed for obtaining further important information about the activity of these compounds as therapeutics in dementia." (PMID 35745206, 2022). "In support of our results, AChE activity was found to be reduced by 27% in a small PET study of patients with DLB and Parkinson’s disease dementia, especially in the medial occipital cortex." (PMID 31511061, 2019). "Our results may have significance in the clinical practice of treatment of AD and other dementia diseases, by neurologists, psychiatrists, geriatricians, internists and general practitioners, as they suggest that oxidative stress may suppresses any potential antioxidant effect of AChE inhibitors." (PMID 30577562, 2018). "Accumulating evidence and post-mortem studies of the brains of patients with dementia revealed low levels of the acetylcholine (ACh) and choline acetyltransferase (CAT) and increased level of acetylcholinesterase (AChE)." (PMID 30018265, 2018). "In an in vivo study as a model of dementia treated with SCOP, cholinergic neurotransmission was obstructed leading to an increase of the AChE and impaired cognition." (PMID 24194776, 2013). "AChE-specific activity was significantly lowered in the detergent-soluble fraction (DS) of the 30 and 60 mg/kg G. biloba-treated dementia groups (p < 0.001, indicating a significant difference from the SCO-treated dementia group)." (PMID 40002547, 2025). "Studies using single-photon emission computed tomography (SPECT) and PET have shown that AChE activity is more extensive and significantly reduced in patients with PD and dementia compared to those without dementia." (PMID 40108903, 2025). "Three of these proteins, neurofilament light polypeptide (NEFL), acetylcholinesterase (ACHE), and pTau181 were uniquely upregulated in participants with dementia and not in MCI participants." (PMID 39649596, 2024).
dementia (continued). "This was reflected in its stronger AChE-inhibitory activity, increased noradrenaline neurotransmission, the activation of BDNF/CREB signaling, and pronounced anti-apoptotic effects in the cortex and hippocampus of rats with experimental dementia." (PMID 39684486, 2024). "The detection of acetylcholinesterase (AChE) and acetylthiocholine (ATC) are of relevance to the studies that examined neurological diseases such as Alzehimer’s, multiple sclerosis, Parkinson’s, dementia, and myasthenia gravis." (PMID 33023140, 2020). "NICE guidance on the prescribing of drugs for dementia aligned with trend changes for NMDA receptor antagonists but not AChE inhibitors." (PMID 29843807, 2018). "PET studies using [11C]MP4A and [11C]PMP have demonstrated mild to moderate decreases in cortical AChE activity in PD patients without dementia, and severe decreases in PDD and DLB patients." (PMID 26984612, 2016). "Nowadays, there is no effective treatment for AD, although AChE inhibitors can attenuate AD symptoms, especially on dementia; they have limitation on improvement of the progression of the disease and side effects." (PMID 27761145, 2016). "Three of the DESH patients and 5 of the non-DESH patients were already prescribed AChE inhibitors for their dementia." (PMID 24731502, 2014). "However, our study group with other dementia was heterogeneous with few cases of each specific diagnosis such as VaD, and larger studies than the present one are therefore needed to evaluate whether the degree of downregulation of CSF AChE activity is disease-specific in dementing disorders." (PMID 24312390, 2013). "An intriguing investigation on the implications of activity and molecular form alterations in AD discovered that AChE in glycosylated AChE form in the frontal cortex and CSF of Alzheimer’s patients differs from that in non-AD populations, including those with different kinds of dementia." (PMID 40429850, 2025). "We hypothesized that the reduced AChE and elevated SOD levels may have contributed in the recovery of the behavioral alteration patterns detected in the mirror biting assay by boosting the total antioxidant and anti-dementia activity in the acclimation process." (PMID 32156000, 2020). "Although acetylcholine esterase (AchE) inhibitors such as donepezil and galantamine and N-methyl-D-aspartate receptor blockers such as memantine have been established to be effective in improving the symptoms of dementia, they have not been shown to change the long-term outcome of the disease." (PMID 33199752, 2020).
memory impairment (125 papers, 2012 to 2026). "This is because high cholesterol can significantly reduce ACHE activity, causing memory impairments in hyperlipidemic rats." (PMID 40989883, 2025). "The decline in ACh levels due to increased AChE activity is a hallmark of AD, contributing to cognitive decline and memory impairment." (PMID 40002547, 2025). "Ginkgo biloba alone or in combination with selenium reversed CdCl2-induced memory impairments, an effect associated with normalizing Ach level as well as AchT and AChE activities in the brain." (PMID 40772264, 2025). "AD has been associated with a decrease of AChE levels in the brain that leads to an abnormal cholinergic neurotransmission, affecting several brain functions, attention, and memory impairment." (PMID 34923590, 2022). "Diminished levels of AChE are reported to cause memory impairment and interfere with the cognitive activities of patients." (PMID 36364190, 2022). "The cholinergic depletion caused memory impairment, as scopolamine did in the amnesic group, by increasing the activity of cholinesterases (AChE and BuChE), which degraded acetylcholine in the synaptic cleft." (PMID 35458662, 2022). "Compounds that enhance AChE level cause memory impairment by decreasing ACh levels, with scopolamine doing the same in the amnesic group." (PMID 34885751, 2021). "Repeated exposure to cadmium causes memory impairment and reduces cell proliferation, neuroblast differentiation, and AChE activity." (PMID 27829466, 2016). "Additionally, hibiscetin was effective in controlling various parameters associated with memory impairment, such as AChE, ChAT activity, antioxidant enzyme levels, and neuroinflammatory parameters." (PMID 38313003, 2024). "Therefore, the inhibition of AchE is considered a potential therapeutic strategy for mitigating the cognitive and memory impairment associated with AD." (PMID 39195183, 2024). "AChE, being the enzyme that breaks down acetylcholine, is fundamental for correct cholinergic transmission and its excessive activity has been many times shown to be associated with cognitive and memory impairments in different experimental models." (PMID 38136170, 2023). "In addition, since new generation of AChE inhibitors targeting in Alzheimer’s-associated memory impairment are currently being inspected in human clinical trials, we examined whether ZN/VB compounds may reduce AChE activity." (PMID 36830589, 2023). "When the AChE activity increases, the concentration of acetylcholine decreases, which may lead to the loss of acetylcholine at cholinergic synapses, and lead to cognitive and memory impairment." (PMID 35991454, 2022). "However, obtain results may suggest that imperatorin may be able to ameliorate memory impairments caused by cholinergic dysfunction through inhibition of AChE activity as well as inhibition of oxidative stress-related processes." (PMID 25189792, 2015). "Several studies have demonstrated the potential of various plant extracts in mitigating SCO-induced memory impairment by inhibiting AChE activity." (PMID 40002547, 2025). "In TMT-induced memory impairment models, Poncirus trifoliata extract (400–1200 mg/kg) improved learning and memory and reduced AChE activity, highlighting its potential for NDDs." (PMID 40002547, 2025). "Treatment with DCF and DEF resulted in a significant, dose-dependent reduction in AChE activity (p < 0.0001) in the brains of SCO-induced memory-impaired mice." (PMID 40002547, 2025). "Further, recent studies show that I3C mitigated cognitive and memory impairment in global cerebral ischemic rats through attenuating AChE activity, oxidative stress, inflammation, and apoptosis." (PMID 40094833, 2025). "D-(-)-Quinic acid can prevent aluminum-induced memory impairment by inhibiting AChE activity, promoting DNA repair, and inhibiting NF-κB." (PMID 39458923, 2024).